ENSG00000285947 (novel protein)
Gene: Protein-coding gene on chromosome 17 (63,917,203 to 63,931,385, reverse strand). Ensembl gene ENSG00000285947.
Genetic constraint (gnomAD): Loss-of-function variants: 18 observed, 38.09 expected, observed/expected ratio (o/e) 0.47, 90% interval 0.33 to 0.7. Missense variants: 375 observed, 404.74 expected, observed/expected ratio (o/e) 0.93, 90% interval 0.85 to 1.01. Synonymous variants: 169 observed, 170.65 expected, observed/expected ratio (o/e) 0.99, 90% interval 0.87 to 1.12.